SNAI2 (snail family transcriptional repressor 2)
Diseases named in the same sentence as SNAI2 in open-access papers (continued):
Sharing a sentence is not in itself a finding about the gene and the disease.
glioma (34 papers, 2010 to 2026). A benign or malignant brain and spinal cord tumor that arises from glial cells (astrocytes, oligodendrocytes, ependymal cells). "In glioma, it was reported that loss of brain-enriched miR-124 enhances stem-like traits and invasiveness by targeting SNAI2." (PMID 39865088, 2025). "The current study aimed to investigate the effects associated with SNAI2 on the proliferation of glioma stem cells (GSCs) to elucidate its underlying molecular mechanism in the development of glioma." (PMID 35654777, 2022). "As previously reported, the expression of SNAI2 was revealed to share positive association with histopathological grade and survival time of patients with glioma, which was involved with the activation of the PI3K/Akt pathway." (PMID 35654777, 2022). "In the current study, we set out to elucidate the role of SNAI2 in the progression of glioma while exploring the relevant underlying mechanism." (PMID 35654777, 2022). "The frequency and extent of SNAI2/Slug mRNA overexpression exceeded that of 26 of the 30 invasion/migration-related transcription factors examined, several of which have been implicated specifically in glioma invasion." (PMID 20565806, 2010). "Our study provides insight into the potential of anti-SNAI2-targeted therapy for glioma treatment, but requires further study and future validation." (PMID 35654777, 2022). "Overall, our study discovered the oncogenic role of SNAI2 in glioma was achieved by PHLPP2 downregulation-activated Akt pathway." (PMID 35654777, 2022). "The mRNA and protein expression of SNAI2 in GSCs was markedly higher than that in A172 glioma cell line relative to the human astrocytes, which was highlighted by the RT-qPCR and Western blot assay findings." (PMID 35654777, 2022). "Previous literature has highlighted the oncogenic transcriptional repressor role of SNAI2 in the development of glioma." (PMID 35654777, 2022). "Intriguingly, a previous study emphasized SNAI2 as an oncogenic transcriptional repressor in the development of glioma." (PMID 35654777, 2022). "The Kaplan–Meier method was performed to analyze the correlation between the expression of SNAI2 and the OS of patients with glioma." (PMID 35654777, 2022). "All these previous studies lend support to our findings indicating that SNAI2 promotes the proliferation of GSCs in vitro and facilitated glioma tumor growth in vivo." (PMID 35654777, 2022). "The RT-qPCR and Western blot assay results revealed that the expression of SNAI2 in the glioma tissues was significantly higher than in that of the normal adjacent normal tissues (p < 0.05)." (PMID 35654777, 2022). "We subsequently determined the expression of SNAI2 in 80 glioma tissues as well as 80 adjacent normal tissues." (PMID 35654777, 2022). "Next, to further determine the expression of SNAI2 in glioma cells, we collected glioma cell lines A172, LN229, and SHG-44 and selected human astrocytes as the control." (PMID 35654777, 2022). "Initially, our results revealed that SNAI2 is upregulated in glioma tumors, which was found to be negatively correlated with the OS of patients with glioma." (PMID 35654777, 2022). "Growth curves indicated that glial tumors overexpressing SNAI2/Slug grew at a significantly faster rate in vivo than did control tumors (P < 0.007 at 4 weeks, t-test)." (PMID 20565806, 2010). "The effects of SNAI2/Slug on glioma growth are likely related to the Slug-induced increase in DNA synthesis observed in glioblastoma cells in the current study." (PMID 20565806, 2010). "Our findings demonstrate that aberrant expression of SNAI2/Slug, a master transcriptional regulator of invasion, contributes to this invasive behavior in gliomas." (PMID 20565806, 2010). "SNAI2 mRNA expression correlated with histologic grade and invasive phenotype in primary human glioma specimens, and was induced by EGF receptor activation in human glioblastoma cells." (PMID 20565806, 2010).
glioma (continued). "We show here that SNAI2/Slug is overexpressed in a subpopulation of glioblastomas in an EGF-dependent manner, and SNAI2/Slug mRNA expression correlates with increasing tumor grade and invasive phenotype in human gliomas." (PMID 20565806, 2010). "To determine the consequences of SNAI2/Slug overexpression in human gliomas, we first generated an IRES-EGFP lentivirus containing the human SNAI2 gene." (PMID 20565806, 2010). "We observed that SNAI2/Slug expression correlates with histologic grade and tumor subtype, such that the most invasive gliomas (glioblastomas) displayed the highest levels of SNAI2/Slug expression." (PMID 20565806, 2010). "The results indicated that the OS of patients with high SNAI2 expression was notably lower than that of the patients with low expression of SNAI2, suggesting that high expression of SNAI2 was related to poor prognosis of patients with glioma." (PMID 35654777, 2022). "Our data validated the initial hypothesis that SNAI2 was an oncogene for glioma through activation of the Akt pathway by downregulating PHLPP2 expression." (PMID 35654777, 2022). "Predictions suggested that SNAI2 was highly expressed in glioma." (PMID 35654777, 2022). "al. emphasized the involvement of SNAI2 in glioma cell stem-like properties; A decrease in SNAI2 elicited by overexpressed miR-124 contributed to a reduction in the CD133(+) cell subpopulation and decreased Nestin expression, while suppressing the in vivo tumorigenicity and invasion of glioma cells." (PMID 35654777, 2022). "Moreover, immunohistochemistry results demonstrated that the protein expression of SNAI2 in glioma was markedly higher than that in the normal adjacent normal tissues, and SNAI2 was predominantly distributed in the nuclei." (PMID 35654777, 2022). "In addition, SNAI2 expression was significantly greater in the 15 gliomas than in the five normal brain tissues, and we observed an inverse correlation between SNAI2 and miR-153-5p levels." (PMID 33323548, 2020). "The observed up-regulation of CLOCK might be a consequence of down-regulated miR-124 in glioma which was frequently reported to inhibit tumor cell proliferation and migration through targeting specific genes like Slug, Twist, and Snai2." (PMID 32195174, 2020). "Researchers found that the tumor suppressor activity of miR-124 could be partly due to its inhibitory effects on glioma stem-like traits and invasiveness through Snail homolog 2 (SNAI2)." (PMID 31467878, 2019). "miR-124 suppresses SNAI2 to inhibit glioma invasiveness and induce glioma differentiation." (PMID 26041995, 2015). "MiR-124 also inhibits the expression of SNAI2 in human glioma." (PMID 23940556, 2013). "SNAI2/Slug is overexpressed in glioma cell lines and promotes invasion and growth in human gliomas." (PMID 23826359, 2013). "Finally, we utilized a three dimensional Matrigel invasion assay to determine the effect of SNAI2/Slug expression on glioma invasion." (PMID 20565806, 2010). "We also examined SNAI2/Slug mRNA expression in 5 human glioma cell lines." (PMID 20565806, 2010). "Our data also confirms prior reports that expression of SNAI2 and FAP is directly linked to malignant glioma grade and further showed that they are coordinately upregulated in gliosarcoma, the grade IV glioma with the most overt mesenchymal differentiation." (PMID 20646316, 2010). "Additionally, the transcriptional repressor SNAI2 may promote glioma stem cell proliferation through AKT pathway activation via downregulating PHLPP2." (PMID 41000374, 2025). "In addition, evidence in the literature showed that the expression of specific genes related to EMT like Slug, Twist, and Snai2 are involved in the mechanism by which miR-124 inhibits tumor cell proliferation and migration in gliomas and is related to the expression of CLOCK." (PMID 34361055, 2021).
glioma (continued). "miR-21 overexpression promoted the capacity of glioma cells to migrate and invade and increased the epithelial marker E-cadherin protein, while decreasing the mesenchymal markers VIM, Snai2, and TWIST." (PMID 33085646, 2020). "Overexpression of miR-124 resulted in targeting of Neural Crest Transcription Factor Slug (SNAI2), which in turn inhibits tumorigenicity of gliomas and invasion in vivo." (PMID 26064134, 2015). "The clinical relevance of identified putative TWIST1 targets was established through correlation between TWIST1, SNAI2 and FAP expression levels in 39 human gliomas of different grades." (PMID 20646316, 2010). "In a set of 39 human glial neoplasms using quantitative RT-PCR we found a significant correlation between TWIST1 and SNAI2 (r = 0.72; p = 0.001) and TWIST1 and FAP alpha (r = 0.57, p = 0.001) message levels." (PMID 20646316, 2010). "The highly correlated expression of TWIST1 and mesenchymal target genes SNAI2 and FAP in human gliomas supported the clinical relevance of TWIST1 mesenchymal change." (PMID 20646316, 2010). "Compared to normal brain controls, the mean TWIST1, SNAI2 and FAP expression were all up-regulated in the most malignant grade IV gliomas compared with grade II and III tumors (p = 0.022, p = 0.0014, p = 0.005, respectively)." (PMID 20646316, 2010). "To confirm that putative TWIST1 targets play a role in glioma cell invasiveness, we overexpressed SNAI2 in SNB19 cells and found that SNAI2 was sufficient to increase SNB19 cell invasion 80%." (PMID 20646316, 2010). "Finally, the roles of SNAI2 and PHLPP2 were verified in glioma growth in nude mice xenografted with tumor." (PMID 35654777, 2022). "We used three GSC cultures and glioma resections to examine the expression, regulation, and role of two transcription factors, SLUG (SNAI2) and TAL1 (SCL), involved in epithelial to mesenchymal transition (EMT), hematopoiesis, vascular identity, and treatment resistance in various cancers." (PMID 34771555, 2021). "We also evaluated the expression levels of the epithelial marker E- cadherin, N-cadherin, SNAI2, CD44, and vimentin in treated U87 and U251 cells to examine whether EMT is regulated by ZBC260 in glioma cells." (PMID 33093476, 2020). "However, a role for SNAI2/Slug in human gliomas has not been reported previously." (PMID 20565806, 2010). "As EMT induction factor, transcription factors, the expression of SNAI1, SNAI2, TWIST1, and PDGFB was significantly higher in high-grade, elderly glioma patients, IDH-wildtype, 1p19q non-codel glioma patients." (PMID 32154177, 2020).
hepatocellular carcinoma (26 papers, 2012 to 2025). A malignant tumor that arises from hepatocytes. "Moreover, FOXS1 induced by TGFβ promoted a classical model of EMT by activating the expression of EMT-transcription factors (SNAI1, and SNAI2) in hepatocellular carcinoma." (PMID 35898871, 2022). "Our study suggests that SNAI2 influences drug sensitivity in HCC cells, which will shed new insights on mechanisms of multidrug resistance of hepatocellular carcinoma." (PMID 27760172, 2016). "Furthermore, SMYD3 binds and activates the Snail family transcriptional repressor 2 (SNAI2) promoter, leading to increased levels of H3K4me3, H3K9Ac, and H3K14Ac; thus, the coexpression of SMYD3 and ANKDH1 is associated with poor prognosis in hepatocellular carcinoma patients." (PMID 39482529, 2024). "In hepatocellular carcinoma cell lines (MHCCLM3, SMMC-7721), MDR was increased by augmented levels of ABCB1, ABCB1 and ABCG2 when SLUG (SNAI2) was downregulated." (PMID 35582031, 2021). "Furthermore, HHT suppressed the PI3K/AKT/Glycogen Synthase Kinase 3β (GSK3β) signaling pathway and decreased snail family transcriptional repressor 2 (Slug) expression, ultimately suppressing EMT in hepatocellular carcinoma cells." (PMID 39949739, 2025).
glioblastoma (22 papers, 2010 to 2025). The most malignant astrocytic tumor (WHO grade IV). "Studies have indicated that when upregulated in a sequential manner with lose-dose BIX01294 treatment, SNAI2 aids in promoting the migration and metastasis of glioblastoma cells." (PMID 35654777, 2022). "This study also demonstrated that miR-203 inhibited EMT and glioblastoma cell chemoresistance by targeting Snail Family Transcriptional Repressor 2 (SNAI2)." (PMID 35330864, 2022). "SNAI2-null mice are reported to have retarded epithelial migration rates, and SOX3 has been implicated in the malignant behaviour of glioblastoma, EMT, and in the promotion of migration and invasion of osteosarcoma cells." (PMID 31430931, 2019). "It was also reported to suppress chemoresistance in human glioblastoma by promoting epithelial-mesenchymal transition via SNAI2." (PMID 28187000, 2017). "Preliminary analysis in our laboratory indicates that SNAI2 mRNA is indeed upregulated in the mesenchymal subclass of glioblastomas (unpublished observations)." (PMID 20565806, 2010). "The U87 human glioblastoma cell line was chosen for these studies because it displayed a high endogenous level of SNAI2/Slug mRNA and protein expression." (PMID 20565806, 2010). "We observed a significant increase in SNAI2 mRNA and protein in U251 glioblastoma cells after EGF exposure." (PMID 20565806, 2010). "We also examined the effect of SNAI2/Slug on chemotaxis in glioblastoma cells using a transwell migration assay and 10% serum as a chemoattractant." (PMID 20565806, 2010). "First, we injected U251 glioblastoma cells transduced with a SNAI2/Slug lentivirus or a control lentivirus subcutaneously into the flanks of nude mice." (PMID 20565806, 2010). "Taken together, these results indicate that enforced overexpression of SNAI2/Slug increases migration and invasion in human glioblastoma cells." (PMID 20565806, 2010). "In vitro growth assays indicated that glioblastoma cells overexpressing SNAI2/Slug grew significantly faster than control cells (P < 0.03, t-test)." (PMID 20565806, 2010). "After SNAI2/Slug knockdown, significantly fewer U87 glioblastoma cells invaded through the matrix when compared to cells expressing an empty control vector (24 +/- 2 cells/hpf vs. 47 +/- 5 cells/hpf, P < 0.0001, t-test)." (PMID 20565806, 2010). "On average, human glioblastoma cells overexpressing SNAI2/Slug formed larger tumors than did control cells." (PMID 20565806, 2010). "We found that significantly more U251 glioblastoma cells overexpressing SNAI2/Slug passed through the matrix than did control cells (83 +/- 10 cells/hpf versus 59 +/- 7 cells/hpf, P < 0.001, t-test)." (PMID 20565806, 2010). "Taken together, these findings indicate that endogenous SNAI2/Slug promotes the migration and invasiveness of human glioblastoma cells." (PMID 20565806, 2010). "A plot of VEGF mRNA expression versus SNAI2/Slug mRNA expression in 20 human glioblastoma specimens revealed a weak but positive correlation." (PMID 20565806, 2010). "Moreover, the upregulation of SNAI2 by zinc-fingers and homeoboxes 1 has been reported to accelerate the proliferation and invasion of glioblastoma cells." (PMID 35654777, 2022). "Moreover, a previous study indicated that the expression of SNAI2 was elevated in imatinib-resistant glioblastoma cells and was higher in patients with glioblastoma than in those with relapsed glioblastoma." (PMID 35654777, 2022). "We also demonstrate that SNAI2/Slug promotes invasion and growth in human glioblastomas." (PMID 20565806, 2010). "Glioblastoma cells overexpressing SNAI2/Slug migrated approximately 62 μm from the edges and covered 63% of the scratch defect, while control cells expressing the empty IRES-EGFP vector migrated only 39 μm from the edges and covered less than 39% of the scratch defect (P < 0.00001, t-test)." (PMID 20565806, 2010).
glioblastoma (continued). "By using the RNA seq database from the Human Glioblastoma Cell Culture resource, SLUG (SNAI2) was significantly more expressed in GSC cultures with a mesenchymal phenotype, while TAL1 expression was not specific to any subtype." (PMID 34771555, 2021). "Additional evidence for a correlation between SNAI2/Slug and VEGF was obtained using mRNA microarray data from primary glioblastoma samples." (PMID 20565806, 2010). "We confirmed overexpression of SNAI2/Slug mRNA by real-time PCR in 9 low grade astrocytomas (LGA) and 17 glioblastomas (GBMs)." (PMID 20565806, 2010). "Previous reports have highlighted the upregulation of SNAI2 in glioblastoma tissues when compared with that in non-neoplastic white matter, which is consistent with the observations of our study." (PMID 35654777, 2022). "Perhaps the strongest evidence for an EMT-like process in glioblastoma is the activity of classical EMT transcription factors and other well-described EMT-promoting pathways, such as ZEB1/ZEB2, TWIST1, WNT/β-catenin pathway and SNAI2/SLUG." (PMID 34680444, 2021). "Importantly, SNAI2/Slug expression is increased by EGFR activation and promotes a mesenchymal phenotype in glioblastoma cells." (PMID 20565806, 2010). "To determine the role of EMP3 on EMT in glioblastoma, we first performed a correlation analysis of gene expression, which showed that EMP3 was positively correlated with VIM, FOS, SNAI2 and TWIST1 (p < 0.001, R: VIM: 0.754, FOS:0.382, SNAI2: 0.498, TWIST1: 0.605)." (PMID 38229014, 2024). "Importantly, SNAI2/Slug mRNA expression was significantly higher in glioblastomas than in low grade diffuse astrocytomas or in non-tumor brain (P < 0.006, t-test)." (PMID 20565806, 2010).
breast tumor (18 papers, 2006 to 2024). "Studies have also shown that high SNAI2 expression in primary ER- breast tumors correlates with poor prognosis in those patients." (PMID 29921289, 2018). "Together, this suggests that ZFHX1B and SNAI2 are the predominant transcriptional regulators of CDH1 accounting for the EMT phenotype of breast tumour cell lines." (PMID 16495925, 2006). "Absence of E-cadherin and SNAI2 expression in the breast tumor tended to be associated with the first distant metastases in the skin (or the subcutaneous tissue)." (PMID 21914172, 2011). "The METABRIC database (1904 human breast tumors) consistently revealed a positive association of NME4 with epithelial markers CDH1 and KRT18 and a negative association with mesenchymal markers CDH2 and VIM as well as many EMT drivers like ZEB1, ZEB2, SNAI2, TWIST1, and TWIST2." (PMID 34674701, 2021). "CDH1 and ELF3 were expressed at a significantly higher level in cells with an epithelial morphology, whereas FN1, FOSL1, VIM, ZFHX1B, SNAI2, SERPINE1 and TFGB1 showed a higher expression in fibroblastic breast tumour cells." (PMID 16495925, 2006). "The negative correlation between ELF5 and SNAI2 expression seen in breast tumor clinical samples is similar to that observed in PPB specimens, suggesting that the decreased expression of ELF5 in PPB lung specimens can promote EMT." (PMID 33158935, 2020).